OAF (out at first homolog)
Synonyms: NS5ATP13TP2; MGC52117
Tractability: Antibody: UniProt predicts a signal peptide or a membrane-spanning region. PROTAC: its protein half-life has been measured.
Gene: Protein-coding gene on chromosome 11 (120,211,032 to 120,230,334, forward strand). Ensembl gene ENSG00000184232.
Subcellular location (Human Protein Atlas): Nucleoplasm; Predicted to be secreted
Genetic constraint (gnomAD): Loss-of-function variants: 11 observed, 19.14 expected, observed/expected ratio (o/e) 0.57, 90% interval 0.36 to 0.95. The upper end of that interval is the gene's LOEUF score, 0.95, which puts it in group 4 of 6, group 1 being the genes least tolerant of losing a copy. Missense variants: 269 observed, 286.24 expected, observed/expected ratio (o/e) 0.94, 90% interval 0.85 to 1.04. Synonymous variants: 128 observed, 120.85 expected, observed/expected ratio (o/e) 1.06, 90% interval 0.92 to 1.23.
Homologues: Orthologues: chimpanzee OAF (99% identical), macaque OAF (96% identical), pig OAF (89% identical), dog OAF (88% identical), mouse Oaf (86% identical), rat Oaf (86% identical), guinea pig OAF (83% identical), rabbit OAF (65% identical), zebrafish oafa (56% identical), zebrafish oafb (50% identical), Drosophila melanogaster oaf (41% identical).
Diseases named in the same sentence as OAF in open-access papers:
OAF is named in the same sentence as 7 diseases in open-access papers, as found by Europe PMC text mining. Sharing a sentence is not in itself a finding about the gene and the disease. The quoted sentences say what the papers report.
asthma (1 paper, 2023). "We screened seven candidate diagnostic biomarkers for asthma using LASSO regression (namely, BCL10, CD300E, IER2, MMP13, OAF, TBC1D3, and TMEM151A), among which the area under the curve (AUC) value for CD300E and IER2 were 0.722 and 0.856, respectively." (PMID 37259023, 2023).
OAF also shares sentences with these, for which no sentence is quoted: gout (1 paper); hyperlipidaemia (1); Hypertension (1); kidney disease (1); polycystic kidney disease (1); pulmonary tuberculosis (1).